TNF (tumor necrosis factor)
Diseases named in the same sentence as TNF in open-access papers (continued):
Sharing a sentence is not in itself a finding about the gene and the disease.
atherosclerosis (continued). "IL-1 and TNF-α are involved in the proliferation and differentiation of VSMCs, the activation of monocytes and macrophages, and the secretion of various inflammatory mediators in the pathogenesis of atherosclerosis." (PMID 39796562, 2024). "Soluble mediators IL-6, TNF-α, and D-dimer are associated with chronic HIV infection as well as various drivers of atherosclerosis including endothelial dysfunction, increased carotid intima-media thickness (cIMT), and transmigration of inflammatory subsets of monocytes." (PMID 39000373, 2024). "Among the 171 pathways, the HIF-1 signaling pathway, TNF signaling pathway, and lipid metabolism and atherosclerosis pathways encompassed the most core targets (five targets each), with the HIF-1 signaling pathway showing the highest level of statistical significance." (PMID 39524878, 2024). "According to the KEGG research findings, the pathways of AA for the treatment of AS primarily involve lipid metabolism-related signals (lipids and atherosclerosis and PPARγ signaling pathways) and inflammatory response-related signals (IL-17 and TNF signaling pathways)." (PMID 39065817, 2024). "The results showed that these differentially expressed genes were mainly enriched in viral protein interaction with cytokine and cytokine receptor, VEGF signal pathway, TNF signal pathway, NF-kappa B signaling pathway, fluid shear stress, atherosclerosis, etc.." (PMID 38650036, 2024). "For example, serum estradiol (E2) regulates G protein-coupled estrogen receptors, reducing the production of inflammatory factors, such as IL-6 and TNF-α, and thereby significantly lowering the body's inflammatory response; this has been shown to inhibit the progression of atherosclerosis." (PMID 38807036, 2024). "KEGG pathway enrichment analysis revealed that GJZLP treatment for tuberculosis could target multiple signaling pathways, primarily including Lipid metabolism, Atherosclerosis, TNF, IL-17, Toll-like receptor and C-type lectin receptor signaling pathway." (PMID 39015338, 2024). "During this process, a large number of CD8+ T cells are present, and their secretion of tumor necrosis factor-α (TNF-α) and interleukin-6 (IL-6) causes low-grade systemic inflammation, which is a pathogenic factor for atherosclerosis and cardiovascular diseases." (PMID 38922089, 2024). "The enrichment analysis of gene sets about stroke revealed that compared to control samples, TNF signaling pathway, neutrophil extracellular trap formation, IL-17 signaling pathway, lipid and atherosclerosis, ribosome biogenesis in eukaryotes, and primary immunodeficiency." (PMID 38166912, 2024). "The KEGG enrichment analysis showed that DENRGs were mainly enriched in pathways related to necroptosis, apoptosis, TNF signalling pathway, neurodegeneration‐multiple diseases, platinum drug resistance, lipid and atherosclerosis, alcoholic liver disease and viral infection‐related pathways." (PMID 39031474, 2024). "GV1001 remarkably blocked the in vitro EndMT caused by TNF-α and Pg LPS, indicating that the preventive effect of GV1001 on Pg-induced atherosclerosis might be partly due to GV1001’s anti-EndMT effect." (PMID 38892314, 2024). "CD86, a biomarker of M1-type macrophages, is markedly expressed in vulnerable arterial plaques.M1-type macrophages release ROS and pro-inflammatory cytokines, such as TNF-α, IL-1β, IL-6, and IL-12, which damage endothelial cells and blood vessels and promote atherosclerosis." (PMID 38382092, 2024). "KEGG-enriched terms were associated with pathways related to the AGE-RAGE signaling pathway, lipid, and atherosclerosis, as well as IL-17 and TNFα signaling pathway, indicating that PV exerts its activity through modulation of oxidative stress and inflammatory pathway." (PMID 38731418, 2024). "Besides, the serum levels of IL-6 and TNF-α were significantly higher in patients with atherosclerosis as compared with normal volunteers." (PMID 38424494, 2024).
atherosclerosis (continued). "MMP9 correlated with left ventricular dysfunction after myocardial infarction, atherosclerosis coronary artery disease, and is increased by proinflammatory cytokines, such as interleukin-1 (IL-1), IL-6 and tumor necrosis factor α (TNFα)." (PMID 39273682, 2024). "The bioinformatics findings suggest that Roxadustat may influence integrin adhesion and affect the TNF and NF-κB signaling pathways, along with lipid and atherosclerosis pathways, potentially reducing inflammation." (PMID 38962312, 2024). "Elevated TNFα levels seem to be connected with the progression of atherosclerosis." (PMID 39452935, 2024). "Enrichment analysis revealed that ginseng might exert protective effects against AIC via multiple molecular pathways, including AGE-RAGE in diabetic complications, fluid shear stress and atherosclerosis, and TNF signaling pathway." (PMID 39243097, 2024). "Several studies have revealed the intervention of TNFα in the pathogenesis of atherosclerosis." (PMID 38672515, 2024). "The enrichment analysis results indicated that the molecular signaling mechanisms underlying the protective effect of ginseng against AIC primarily involved AGE-RAGE in diabetic complications pathway, Fluid shear stress and atherosclerosis, and TNF signaling pathway." (PMID 39243097, 2024). "Moreover, USP20 alleviates inflammation in SMCs in TNF and IL-1β-induced atherosclerosis by deubiquitinating RIPK1, a vital factor of inflammation and cell death." (PMID 38322269, 2024). "Increased accumulation of oxidized lipids leads to atherosclerosis through the activation of proinflammatory pathways and the increase of proinflammatory cytokines such as interleukin- (IL) 1beta, tumor necrosis factor-alpha (TNF-alpha), and nuclear factor-kB (NF-kB)." (PMID 38399451, 2024). "TNF-α is involved in the acceleration of atherosclerosis and rupture of atherosclerotic plaques." (PMID 39367448, 2024). "The serum levels of IL-6, TNF-α and IL-1β were increased in atherosclerosis group." (PMID 38424494, 2024). "Both atherosclerosis and autoimmune diseases are driven by inflammatory processes, and research has shown that proinflammatory cytokines such as tumor necrosis factor-alpha (TNFα) and interferon-gamma (IFNγ) can synergistically induce RNF213 expression, leading to angiogenesis in vitro and in vivo." (PMID 39857601, 2024). "The KEGG analysis showed that the upregulated genes in cMono were enriched in Tuberculosis, lipid and atherosclerosis, Epstein-Barr virus infection, TNF signaling pathway, NF-kB signaling pathway, Toxoplasmosis, IL-17 signaling pathway, Th17 cell differentiation, Legionellosis, and Leishmaniasis." (PMID 38552230, 2024). "Furthermore, it can induce macrophages to secrete a greater quantity of atherosclerosis‐associated molecules, including MCP‐1, TF, and TNF‐α, and increase the uptake of oxLDL, thereby accelerating the formation of foam cells." (PMID 39508636, 2024). "Moreover, KEGG pathway analysis demonstrated that these genes were predominantly involved in pathways associated with lipid and atherosclerosis, MAPK signalling pathway, NF‐kappa B signalling pathway, TNF signalling pathway and FoxO signalling pathway." (PMID 38702954, 2024). "TNF-α has an important effect on the advancement of endothelial dysfunction and atherosclerosis." (PMID 39065817, 2024). "Combined with TNF-α levels, IL-6 levels may improve the prediction of atherosclerosis development in these patients." (PMID 39766337, 2024). "Furthermore, butyrate treatment of Ea.hy926 cells has been found to reduce ox-LDL uptake, CD36, VCAM-1, TNF-α, and interleukin-1β/6 production while increasing IL-10 production, suggesting its potential as a treatment for atherosclerosis." (PMID 39275259, 2024). "While TNFα was found in both human and murine arterial walls with atherosclerotic and other lesions, its absence did not reduce lesion size in mice; however, the absence of lymphotoxin-α, a cytokine with homology to TNFα, reduced atherosclerosis." (PMID 38256155, 2024).
atherosclerosis (continued). "The KEGG analysis revealed that DEMs target genes were involved in signaling pathways including pathways of neurodegeneration, PI3K-Akt signaling, Alzheimer’s disease, MAPK signaling, Ras signaling, cAMP signaling, lipid and atherosclerosis, TNF signaling, ErbB signaling, and others." (PMID 39010173, 2024). "KEGG pathway enrichment analysis focused on Lipid and atherosclerosis, IL-17 signaling pathway, Toll-like receptor signaling pathway, TNF signaling pathway, and PI3K-Akt signaling pathway, with the analysis also highlighting key targets within these enriched pathways." (PMID 39654679, 2024). "Additionally, KEGG analysis demonstrated that candidate hub genes predominantly influence lipid metabolism and atherosclerosis, NF—kappa B signaling pathway, cytokine—cytokine receptor interaction, IL−17 signaling pathway, and TNF signaling pathway." (PMID 39024234, 2024). "Thus, inflammatory factors, such as C-reactive protein (CRP), interleukin (IL)-6, and tumor necrosis factor-α (TNF-α), are consistently elevated in atherosclerosis." (PMID 38699583, 2024). "Important signaling pathways including AGE-RAGE signaling pathway in diabetic complications, Fluid shear stress and atherosclerosis, TNF signaling pathway, IL-17 signaling pathway, Lipid and atherosclerosis were identified, which are mainly involved in atherosclerosis and inflammatory response." (PMID 38496269, 2024). "Notably, inflammatory mediators like TNF-α and IL-6 impair nitric oxide production and endothelial function, contributing to atherosclerosis and CVD development." (PMID 39337647, 2024). "In this regard, we should mention that TNF-α secretion increases in age-related pathological processes, such as atherosclerosis, an inflammatory disease that becomes more prevalent with age and pathological conditions, including those caused by viral or subclinical bacterial infections." (PMID 38397814, 2024). "Excessive TNF-α secretion influences the induction of atherosclerosis via the accumulation of cholesterol in the endothelium and inhibits the production of nitric oxide (NO), a vasodilator, in vascular endothelial cells, thereby also triggering endothelial dysfunction." (PMID 39742290, 2024). "Moreover, KEGG enrichment analysis indicated that the overlapping targets of kaempferol and OP were predominantly associated with signaling pathways implicated in atherosclerosis, the AGE/RAGE signaling pathway, and the TNF signaling pathway." (PMID 38528143, 2024). "TNF signaling route, Herpes simplex virus 1 infection, viral protein interaction with cytokine and cytokine receptor, malaria, lipid and atherosclerosis, PPAR signaling pathway, and PPAR signaling pathway were all enriched for among the C-DEGs in the KEGG enrichment analysis." (PMID 38653779, 2024). "An increase in pro-inflammatory cytokines, including IFN-y, IL-1β, and tumor necrosis factor (TNF)-α, is related to atherosclerosis promotion and progression, while IL-10, IL-33 and transforming growth factor (TGF)-β are associated with atheroprotective properties." (PMID 38397127, 2024). "Our KEGG enrichment analysis indicated that these targets were mainly enriched in pathways such as Fluid shear stress and atherosclerosis, AGE-RAGE signaling pathway in diabetic complications, Lipid and atherosclerosis, IL-17 signaling pathway, and TNF signaling pathway." (PMID 38167125, 2024). "KEGG pathway analysis revealed enrichment in the IL-17 signaling pathway, endocrine resistance, hepatitis B, lipid and atherosclerosis, proteoglycans in cancer, relaxin signaling pathway, leishmaniasis, fluid shear stress and atherosclerosis, malaria, and TNF signaling pathway." (PMID 39640883, 2024). "The studies conducted suggested that adding a TNF-α inhibitor to conventional therapy may constitute a new treatment strategy for elderly patients with atherosclerosis." (PMID 39684812, 2024).
atherosclerosis (continued). "TNF can promote the production of inflammatory cytokines, exacerbate inflammatory responses, and participate in regulating the function to vascular endothelial cells, affecting the progression of atherosclerosis." (PMID 39677038, 2024). "We then analyzed the level of IL-1β, IL-18, TNF-α and NF-κB p65 in arteries of atherosclerosis." (PMID 36759876, 2023). "On the other hand, TNF alpha production increases in individuals who eat a high-fat diet, inducing endothelial dysfunction, which could worsen atherosclerosis." (PMID 36979696, 2023). "On the other hand, TNF inhibitors may stabilize or slow down the progression of subclinical atherosclerosis and endothelial dysfunction in AS patients." (PMID 37109438, 2023). "Moreover, the bioinformatics analyses and validations revealed that the AR exerted the effects by acting on lipid and atherosclerosis, the TNF-α signaling pathway, NF-kappa B signaling pathway, and neuroactive ligand–receptor interaction." (PMID 37361203, 2023). "Furthermore, chronic inflammatory processes, and specifically the concentration of TNF-α, drive cardiovascular events, such as atherosclerosis, atherothrombotic disease, and venous thromboembolism." (PMID 37568441, 2023). "If inflammation indeed drives atherosclerosis, targeting TNF-α and IL-6 could be promising strategies to reduce cardiovascular disease risk." (PMID 37893519, 2023). "The exhibition of the M1 phenotype by several factors (e.g., interferon-gamma, tumor necrosis factor α (TNFα), lipopolysaccharide) leads to anti-bacterial, anti-virus, and anti-tumoral activity and the induction of type II diabetes, atherosclerosis, and autoimmune disease." (PMID 37762869, 2023). "The chronic inflammation process, which is mediated by several factors, including cell-derived proinflammatory cytokines such as tumor necrosis factor-alpha (TNFα) and interleukin (IL)-1 and IL-6, contributes to the development of endothelial dysfunction, atherosclerosis, and CVD." (PMID 37107323, 2023). "IL-1β knockdown significantly downregulated TNF-α, IL-6, and IL-8, which implied IL-1β cytokine could be a pharmacological target to prevent atherosclerosis induced by cigarette smoke." (PMID 36791122, 2023). "Diosgenin prevents atherosclerosis by downregulation of TNF-α and NF-κBp65 markers." (PMID 37520342, 2023). "In cardiovascular diseases, NF-kB activation is associated with the production of pro-inflammatory cytokines, such as interleukin-6 (IL-6) and tumor necrosis factor (TNF), and the promotion of vascular inflammation, endothelial dysfunction, and atherosclerosis." (PMID 37047011, 2023). "Because vascular cell adhesion molecule 1 (VCAM-1) plays a major role in atherosclerosis, we investigated whether Shank3 modulates the tumor necrosis factor-α (TNF-α)–induced expression of VCAM-1." (PMID 37947623, 2023). "In addition, dendritic cell exosomes contribute to endothelial inflammation and atherosclerosis via the membrane TNF-a- mediated NF-κB pathway." (PMID 37965089, 2023). "Additionally, RC can induce the apoptosis of endothelial cells by increasing the secretion of tumor necrosis factor-alpha (TNF-α) and interleukin (IL)-1β, further promoting the formation of atherosclerosis." (PMID 37767252, 2023). "These analyses revealed that SGLT-2i treatment substantially reduces not only macrophage infiltration but also the suppression of inflammatory M1 markers, including tumor necrosis factor-alpha, interlukerin-1 (IL-1), and IL-6, which play a significant role in the improvement of atherosclerosis." (PMID 38813008, 2023). "Several proposed mechanisms have been elucidated, for example, human immunodeficiency virus, herpesviruses, and Chlamydia pneumoniae may accelerate atherosclerosis through the induction of TNF-α and IL-2 in response to antigens." (PMID 37104297, 2023).
atherosclerosis (continued). "MONO are involved in vascular accumulation, upregulation of IL-1β, IL-6 and TNF-α expression in the brain, formation of reactive oxygen species (ROS), promotion of angiotensin-II (AngII) and other mechanisms that form atherosclerosis, brain injury, heart and kidney injury." (PMID 37265570, 2023). "Since the combined blockade reduced atherosclerosis within the carotid artery, the site in which the fat transplant was located, our results suggest that the combined blockade of TNFα, CXCL2 and CCL2 reduced the ability of aged visceral fat to enhance atherosclerosis, at least locally." (PMID 36683460, 2023). "Interestingly, basal circulating IL-1β and TNF-α are higher in men compared to women and their response is also higher in males in several diseases like atherosclerosis and vasculitis." (PMID 37810621, 2023). "Notably, patients with RA are at an increased risk of premature death due to accelerated atherosclerosis in cardiovascular comorbidities, while NLRP3 inflammasome activation and production of IL-1β, TNF-α, and IL-6 are also key immune mediators of RA." (PMID 37720032, 2023). "Temporary hypocortisolism may lead to subsequent increase of inflammatory markers being involved in atherosclerosis such as Interleukin 1 (IL-1), Interleukin 6 (IL-6), and tumor-necrosis factor (TNF)." (PMID 37008924, 2023). "Regarding possible correlations between inflammatory and vascular mediators associated with atherosclerosis, Acidaminococcus (0.25, FDR = 0.02) and Prevotella (0.23, FDR = 0.03) had a positive correlation with TNF‐alpha, whereas Microbacteriaceae (−0.23, FDR = 0.03) had a negative correlation." (PMID 36287108, 2023). "Similar anti-inflammatory effects were observed in atherosclerosis and a cuff-induced vascular inflammation model, where Nifedipine inhibited TNF-α-induced reactive oxygen species (ROS) generation and CCL-2 gene expression, but CCL-2 protein levels were not measured in either of these studies." (PMID 36835507, 2023). "Because it was reported that adenine might suppress inflammatory cytokines secretion and, thus, explain a reduction in atherosclerosis, we tested plasma levels of interleukin 6 (IL-6) and tumor necrosis factor alpha (TNFα)." (PMID 36844738, 2023). "TNFSF14 is a transmembrane protein belonging to the tumor necrosis factor (TNF) ligand family, which may have a pathogenic function in atherosclerosis." (PMID 36676179, 2023). "Former data have documented that IL-6 is not only a significant contributor to the early onset of atherosclerosis but is also a marker of the greater extent of atherosclerotic lesions, involving other pro-inflammatory cytokines, like IL-1 and tumor necrosis factor alpha (TNF-α), as well." (PMID 36835838, 2023). "Being able to perfuse the model with physiological shear stress and addition eLDL or TNF-α, they could trigger early-stage atherosclerosis in this model." (PMID 38135964, 2023). "On the other hands, KEGG pathway annotation analysis indicated that chiefly participated in MAPK signaling pathway, Lipid and atherosclerosis, Neutrophil extracellular trap formation, Cytokine-cytokine receptor interaction, TNF signaling pathway and NF-kappa B pathway." (PMID 37730550, 2023). "The amitriptyline reduced TNF-a-induced Acid SMase/CER and MAPK activation, inhibiting TNF-induced monocyte/EC interactions while decreasing future endothelial inflammation and dysfunction which is linked to atherosclerosis." (PMID 37608809, 2023). "Because vitamin D signaling reduces the expression of TNF-alpha, IL-6, IL-1, and IL-8 in isolated blood monocytes, it may have an impact on the pathogenesis of atherosclerosis." (PMID 36742396, 2023). "TNF-α may induce the production of reactive oxygen species and thereby result in endothelial dysfunction, which is typically the first event in atherosclerosis." (PMID 37947623, 2023). "SMAD3, TNF, MMP2, MMP9, CTGF, CD44 and AKT1 are associated with atherosclerosis." (PMID 37328880, 2023).